Y_RNA (Y RNA )
Gene: Miscellaneous RNA gene on chromosome 6 (99,642,237 to 99,642,347, reverse strand). Ensembl gene ENSG00000199303.
Homologues: Orthologues: chimpanzee Y_RNA (99% identical), macaque Y_RNA (85% identical), guinea pig Y_RNA (84% identical). Paralogues in human: RNY1 (90% identical), Y_RNA (88% identical), RNY1P11 (87% identical), Y_RNA (87% identical), Y_RNA (86% identical), RNY1P15 (85% identical), Y_RNA (85% identical), Y_RNA (84% identical), RNY1P12 (83% identical), RNY1P7 (83% identical), Y_RNA (83% identical), RNY1P10 (82% identical), and 96 more.